PTPN22 (protein tyrosine phosphatase non-receptor type 22)
Diseases named in the same sentence as PTPN22 in open-access papers (continued):
Sharing a sentence is not in itself a finding about the gene and the disease.
diabetes (38 papers, 2007 to 2025). "Predictive of IA (AUC 0.91) and progression to diabetes (AUC 0.92); identified key biomarkers such as serum ascorbate, PTPN22 polymorphism, serum glucose, ADP fibrinogen, and mannose." (PMID 40895926, 2025). "For example, among the candidate genes were known susceptibility loci for diabetes (PTPN22, CEP68, RREB1, TCF7L2), coronary artery disease (PSRC1, UNC5C, LPLA), depression (MAD1L1, YLPM1) and insomnia (NMT1)." (PMID 38541061, 2024). "Particularly, rs2476601 and its associated gene PTPN22 appear to play a crucial role in the connection between type 2 diabetes mellitus, hypothyroidism/mucous oedema and hypoglycaemia." (PMID 39238070, 2024). "This missense variant, located at the promoter region of the PTPN22 gene, appears to play a crucial role in the genetic association between type 2 diabetes mellitus, hypothyroidism/myxoedema and hypoglycaemia." (PMID 39238070, 2024). "In conclusion, we provide the first information on diabetes-associated polymorphisms in PTPN22 in a genetically isolated Armenian population." (PMID 37315092, 2023). "We have provided the first information on diabetes-associated polymorphisms in PTPN22 in a genetically isolated Armenian population." (PMID 37315092, 2023). "Both psoriasis and diabetes are associated with the PTPN22, ST6GAL1, and JAZF1 genes." (PMID 40660159, 2025). "In addition, Ifih1R accelerated streptozocin-induced diabetes incidence in mice expressing a diabetes risk variant of Ptpn22 on a c57BL/6J background, supporting rs1990760 as a causal allele in T1D." (PMID 38487540, 2024). "Our previous findings showed that Ifih1R increased streptozocin (STZ)-induced diabetes incidence as well as synergized with the Ptpn22 diabetes risk variant (mouse model for the rs2476601 human risk variant) to further accelerate and increase STZ-induced diabetes." (PMID 38487540, 2024). "Studies have reported that HLA-DR3, CTLA4, and PTPN22 may be common genetic susceptibility genes for diabetes and hypothyroidism." (PMID 34258276, 2021). "The key predictors of IA included changes in serum ascorbate, 3-methyl-oxobutyrate, and the PTPN22 polymorphism, while serum glucose, ADP fibrinogen, and mannose were significant for diabetes progression." (PMID 40362176, 2025). "Further, due to the presence of a missense variant in PTPN22 gene that is associated with multiple diseases, such as Crohn’s disease, diabetes, and RA, a non-palindromic sequence became perfectly palindromic in 1000G." (PMID 33298903, 2020). "The link between psoriasis and diabetes could, in part, be explained by the rise in obesity and unhealthy lifestyles, the insulin resistance associated with inflammation, and the presence of various genes (CDKAL1, PTPN22, ST6GAL1, JAZF1) linked to both conditions." (PMID 38541672, 2024). "Overexpression of PTPN22 resulted in attenuated Th1 differentiation at low strength T cell receptor (TCR) stimulation and protected mice from a model of diabetes." (PMID 36013501, 2022). "For example, overexpression of PTPN22 resulted in attenuated Th1 differentiation at low strength TCR stimulation and protected mice from a model of diabetes." (PMID 30054208, 2018). "Nonobese diabetic (NOD) mice with Ptpn22 deficiency show reduced numbers of plasma cells, and B-cell-specific ablation of Ptpn22 decreases the incidence of diabetes in NOD mice, suggesting that Ptpn22 variation may contribute to T1D by modifying B-cell maturation." (PMID 36220996, 2022).
Graves disease (33 papers, 2006 to 2025). Graves' disease is an autoimmune disorder that leads to overactivity of the thyroid gland (hyperthyroidism).It is caused by an abnormal immune system response that causes the thyroid gland to produce too much thyroid hormones. "A meta-analysis showed that PTPN22 C1858T is associated with the risk of Grave’s disease and Hashimoto’s thyroiditis in the overall study population." (PMID 36013501, 2022). "Outside the HLA region, the PTPN22 genetic variant rs2476601 has also been shown to be a potential Graves’ disease predictor and together with the HLA variants was included in the Graves’ Events After Therapy + (GREAT+) score." (PMID 34887833, 2021). "The associations of the MAGI3 locus with TPOAb-positivity and Graves' disease may therefore also be explained by linkage with disease-associated variants in PTPN22." (PMID 24586183, 2014). "Among these, PTPN22, CTLA4, HLA_DRB1, FCRL3, and IL2RA are common susceptibility genes between both conditions, while CD40 is exclusively associated with Graves’ disease and RA." (PMID 38093966, 2023). "PTPN22, IL-2RA/CD25, CD40, and SCGB3A2 genes were shown to be associated with Graves’ disease (GD) using candidate gene studies." (PMID 31066758, 2019). "Most genes that have been associated with AITD (predominantly Graves' disease) by candidate gene and GWAS studies so far are located in the HLA class I and II regions, or in genes involved in T-cell (i.e., CTLA-4, PTPN22) or other autoimmune responses." (PMID 24586183, 2014). "Graves’ disease: CTLA4 and PTPN22 variants are linked to Graves’ disease." (PMID 39726471, 2024). "In addition, a gene named protein-tyrosine-phosphate nonreceptor 22 (PTPN22) has previously been reported as a susceptibility locus for Graves’ disease (GD) in European populations." (PMID 24386393, 2013).
Crohn disease (26 papers, 2009 to 2025). A gastrointestinal disorder characterized by chronic inflammation involving all layers of the intestinal wall, noncaseating granulomas affecting the intestinal wall and regional lymph nodes, and transmural fibrosis. "Loss of PTPN22 was found to enhance colitis in mice, while a gain of function PTPN22 variant was associated with increased IL-1β in Crohn’s disease patients." (PMID 38763335, 2024). "Previous study showed PTPN22 C1858T (R620W), a gain of function, was correlated with higher risk of systemic sclerosis, but reduced risk of Crohn’s disease." (PMID 26370572, 2015). "The mechanism behind how PTPN22 genetic variants are associated with Crohn's disease need to be further elucidated." (PMID 26734582, 2015). "While the Trp620 PTPN22 allele is associated with susceptibility in many diseases, the alternative Arg620 allele confers risk in others (such as Crohn's disease)." (PMID 19951419, 2009). "Interestingly, the variant in PTPN22 is associated with reduced risk of Crohn’s disease while loss-of-function mutations in NOD2 are associated with increased risk of Crohn’s disease." (PMID 33717184, 2021). "We also identified colocalizing signals in a number of clinically relevant coding mutations, including sites linking PTPN22 with Crohn’s disease, NIPA with coronary artery disease and platelet trait variation, and the hemochromatosis gene HFE with altered lipid levels." (PMID 32600345, 2020). "A SNP mutation (rs2476601) in PTPN22 is associated with T1D and Crohn's disease." (PMID 26734582, 2015). "Thus PTPN22 C1858T polymorphism, which is associated with systemic sclerosis susceptibility, reduced the risk of Crohn’s disease." (PMID 26370572, 2015). "Seven shared risk genes (CD40, PTPN22, CD226, BATF, PRKCB, RasGRP1, and PTPN2) are involved in cytokine pathways linked to Crohn’s disease." (PMID 40839671, 2025). "Previous studies have shown that protein tyrosine phosphatase non-receptor type 22 (PTPN22) plays an opposing role in Crohn’s disease compared to T1D." (PMID 39350769, 2024). "Research indicates that PTPN22 knockdown activates inflammatory signaling pathways, leading to Crohn’s disease." (PMID 39350769, 2024). "The ordinary failure in the function of protein tyrosine phosphatase, non-receptor type 22 (PTPN22), it minimizes the risk of Crohn’s disease but maximizes the risk of T1D and AIDS." (PMID 32815547, 2020). "The single nucleotide polymorphism (SNP) rs2476601 within the PTPN22 gene locus results in aberrant function of PTPN22 protein and protects from Crohn’s disease (CD)." (PMID 27467733, 2016). "A possible suggestion for future studies is to perform a large-scale GWAS investigation to estimate the incidence of SNP's in PTPN2 and PTPN22 in patients diagnosed with both T1D and Crohn's disease." (PMID 26734582, 2015). "The protein tyrosine phosphatase genes, PTPN2 and PTPN22, are of vital importance to both T1D and Crohn's disease." (PMID 26734582, 2015). "The reduced PTPN22 levels contribute to increased levels of IL-6 found in Crohn's disease." (PMID 26734582, 2015). "The decrease of PTPN22 expression in Crohn's disease could be because TNFα and IL-1β both decrease its expression significantly and thus, play a role in its pathogenesis." (PMID 26734582, 2015). "Besides HLA, protein tyrosine phosphatase non-receptor type 22 (PTPN22) was implicated in both systemic sclerosis and Crohn’s disease." (PMID 26370572, 2015). "For main effects, JAK2, TNFSF15, ZNF365 and PTPN22 showed consistent small P‐values in the original sequencing data as well as the validation with IBD and Crohn's disease data sets." (PMID 29441677, 2018). "This review article is focused on the impact of SNP's in PTPN2 (protein tyrosine phosphatase, non-receptor type 2) and PTPN22 (protein tyrosine phosphatase non-receptor type 22) on the development of Crohn's disease and T1D." (PMID 26734582, 2015).
autoimmune thyroid disease (22 papers, 2008 to 2025). Inflammatory disease of the thyroid gland due to autoimmune responses leading to lymphocytic infiltration of the gland. "Joint susceptibility genes identified for T1DM and autoimmune thyroid diseases, including hypo- or hyperthyroidism, are HLA class II genes, PTPN22, CTLA-4 and FOXP3." (PMID 38116309, 2023). "Our study, for the first time, linked a rare variant of PTPN22 to Hashimoto’s thyroiditis, providing further evidence of the disease-causing or susceptibility role of PTPN22 in autoimmune thyroid disease." (PMID 30384852, 2018). "In a separate study, significantly elevated levels of DNAm were identified in the promoter region of PTPN22 in young patients with HT, relative to controls; this verified the role of PTPN22 as an epigenetically determined susceptibility gene for thyroid autoimmunity." (PMID 38075038, 2023).
psoriasis (19 papers, 2006 to 2025). An autoimmune condition characterized by red, well-delineated plaques with silvery scales that are usually on the extensor surfaces and scalp. "For example, PTPN22 is a psoriasis risk gene with polymorphisms associated with early onset psoriasis, and CYB5R2 is involved in fatty acid metabolism." (PMID 22957057, 2012). "With respect to the R620W variant of PTPN22 in the Newfoundland population, our results are consistent with the reported studies in psoriasis." (PMID 16507123, 2006). "Because the Toronto cohort is the first population to report a significant association between PTPN22 and PsA and contradicts previous larger studies in psoriasis, this result should be interpreted with caution until it is independently validated in another PsA population." (PMID 16507123, 2006). "Two up-regulated IDD genes (HS3ST-1 and PTPN22) were also present in the psoriasis inflammatory DC transcriptome, which contains DEGs between CD11c+CD11c− DCs versus CD11c+CD1+ DCs FACS-sorted from psoriasis lesions." (PMID 22957057, 2012). "A recent study examining genetic profile in a large number of patients with PsA, found that polymorphism in PTPN22 was associated with PsA but not psoriasis." (PMID 38124740, 2023). "Association to NOS2 has previously been reported to psoriasis; however no such association has been made to PTPN22." (PMID 25923216, 2015). "As SNPs at the PTPN22 locus have not previously been reported to be associated to psoriasis susceptibility we investigated this further in two large psoriasis data sets." (PMID 25923216, 2015). "Examples include PTGS2 in psoriasis; PTPN22 in RA and GZMK in IBD." (PMID 20444268, 2010). "We also confirm association of PsA with a previously reported psoriasis locus, NOS2, bringing the total number of confirmed, genome-wide significant, PsA loci to 10 including 4 that are PsA-specific (HLA-B, chromosome 5q31, PsA-specific variants within IL23R and now PTPN22)." (PMID 25923216, 2015). "When comparing psoriasis-involved skin to the adjacent normal skin of patients with psoriasis, differentially methylated CpGs are found, some of which situated at the promoters of known PSORS genes, such as S100A9, PTPN22, SELENBP1, CARD14, and KAZN." (PMID 37628670, 2023). "Several genes reported to be involved in psoriasis pathogenesis including S100A9, S100A8, PTPN22, PTPN6, LAMA4, IL1B and IL12RA were involved in many of these enriched biological processes." (PMID 30092825, 2018). "A pathogenesis involving IL 23R, IL 12B, CDKAL1, and PTPN22 is common to both IBD and psoriasis." (PMID 40981083, 2025).
breast carcinoma (18 papers, 2013 to 2024). "Previous studies have shown that overexpression of PTPN22 significantly inhibits the growth of human breast cancer cells." (PMID 30240439, 2018). "Among the hubs of the 6 modules, 5 of them (PTPN22, BRIP1, CEACAM6, LTF, and CCNT1) have been previously found to be associated with breast cancer, and the other one, MXRA5, has been reported to be related to non-small cell lung cancer." (PMID 30240439, 2018). "In breast cancer, PTPRD was discovered through The Cancer Genome Atlas project to be a novel gene that was frequently mutated in addition to PTPN22, suggesting the emerging roles of protein tyrosine phosphatases in breast cancer associated biological processes." (PMID 26474282, 2015).
vitiligo (17 papers, 2012 to 2025). Generalized well circumscribed patches of leukoderma that are generally distributed over symmetric body locations and is due to autoimmune destruction of melanocytes. "The CT genotype of the PTPN22 rs2476601 polymorphism is more frequent in vitiligo patients; in the case of the NLRP1 rs2670660 polymorphism it was the AG genotype, and in the TYR rs1393350 polymorphism, it was the AG genotype." (PMID 40837363, 2025). "A meta-analysis was conducted of the association between PTPN22 1858 C/T polymorphisms and vitiligo and found PTPN22 C1858T polymorphism is associated with vitiligo susceptibility in European population." (PMID 26870082, 2016). "The aim of the present hospital case-control study was to investigate the possible involvement of the PTPN22 gene 1858C/T polymorphism in Mexican patients with vitiligo from Northeast Mexico." (PMID 25289035, 2014). "In the current study, the presence of the PTPN22 +1858C/T polymorphism in a population affected by vitiligo from northeast Mexico was analyzed." (PMID 25289035, 2014). "There is evidence that the PTPN22 +1858T allele constitutes a generalized risk for vitiligo in a European Caucasian (Romanian) population, highlighting the importance of a genetically mediated autoimmune mechanism in the pathogenesis of vitiligo." (PMID 25289035, 2014). "In conclusion, the present data indicates a possible association between the PTPN22 +1858C/T genotype and a significant susceptibility of developing an active form of vitiligo." (PMID 25289035, 2014). "Recently, a number of genes which play a role in vitiligo susceptibility, including HLA, PTPN22, NALP1, XBP1, FOXP1, IL2RA have been tested for genetic association with vitiligo." (PMID 23284977, 2012). "Indeed, similar to AA, the 1858 C/T missense single nucleotide polymorphism of PTPN22 (R620W; rs2476601) was shown to be associated with a higher vitiligo risk." (PMID 30845666, 2019). "In humans, DDR1, XBP1, NLRP1 and PTPN22 genes have been linked to vitiligo and these genes could be a starting point to investigate if animals with vitiligo are linked to the genes and mutations reported in humans." (PMID 31324191, 2019). "In conclusion, the present data indicate the involvement of the PTPN22 +1858T allele as a genetic risk factor for susceptibility to active vitiligo in the Mexican population, supporting the evidence of the possible involvement of the immune response in the pathogenesis of vitiligo." (PMID 25289035, 2014). "Genome-wide association studies (GWAS) have identified approximately 50 vitiligo-susceptibility genes, including PTPN1, PTPN22, NLRP1, FASLG, and TYR." (PMID 40837363, 2025). "The PTPN22 +1858C/T polymorphism has not been previously assessed for vitiligo in American populations." (PMID 25289035, 2014). "Similarly to AITD, Vitiligo exhibits a non-MHC gene association with PTPN22, the gene encoding lymphoid protein tyrosine phosphatase (LYP)." (PMID 39337081, 2024). "The genetic susceptibility to vitiligo has been studied extensively, identifying several gene loci associated with autoimmune-based thyroid dysfunction: these include genes encoding protein tyrosine phosphatase non-receptor type 22 (or PTPN22), tyrosinase, thyroglobulin (TG), and TSH-R." (PMID 39767917, 2024). "Although one should keep in mind that the actual levels of eCBs have never been investigated in lesional skin of vitiligo patients, and that PTPN22 has other, ECS-independent biological functions, immunosuppressive cannabinoid signaling might have therapeutic value in vitiligo." (PMID 30845666, 2019).